SIRT1 (sirtuin 1)
Diseases named in the same sentence as SIRT1 in open-access papers (continued):
Sharing a sentence is not in itself a finding about the gene and the disease.
Cerebral ischemia (continued). "According to a previous study, mice overexpressing SIRT1 sustained less hippocampal damage following cerebral ischemia (bilateral common carotid artery occlusion) than mice lacking SIRT1, demonstrating that SIRT1 plays a prominent role in brain protection." (PMID 36105479, 2022). "Animal experiments have also shown that RES can play neuroprotective and antioxidant effects on apoptosis induced by cerebral ischemia rats by increasing SIRT1 expression." (PMID 36081910, 2022). "In the present study, we aimed to explore the neuroprotective effects of AS-IV in rats with cerebral ischemia/reperfusion (CIR) injury targeting the Sirt1/Mapt pathway." (PMID 33841157, 2021). "As a new target to study cerebral ischemia injury, SIRT1 is widely distributed in the hippocampus and involved in cellular oxidative stress and apoptosis." (PMID 34658877, 2021). "AS-IV exerted the neuroprotective effects against the damage of cerebral ischemia probably by the activation of Sirt1/Mapt pathway." (PMID 33841157, 2021). "On the other hand, the SIRT1 inhibitor nicotinamide can also protect neurons from excitotoxicity and cerebral ischemia." (PMID 34680562, 2021). "SIRT1 knockout mice had larger infarct sizes than wild-type mice after exposed to MCAO cerebral ischemia." (PMID 33935765, 2021). "To study the functions of miR-19a/b-3p, SPHK1, FoxO3, and SIRT1 in cerebral ischemia, we firstly measured their expression levels during ischemia/ reperfusion (I/R)." (PMID 34051800, 2021). "For example, in a permanent focal ischemia mice model, SIRT1 plays a key role in neuroprotection against brain ischemia by inhibition of inflammatory and apoptotic pathways." (PMID 34899720, 2021). "As the agonist of Sirt1, resveratrol downregulates the Sirt1 protein expression levels and protects neurons from stroke via the Sirt1-dependent manner to elicit ischemic tolerance in the cerebral ischemia condition." (PMID 32089065, 2020). "SIRT1 has also been shown to possess neuroprotective properties in a variety of pathological conditions including neurodegenerative diseases and cerebral ischemia." (PMID 33510613, 2020). "The following sections discuss the effect of SIRT1 on CNS disorders, including cerebral ischemia, traumatic brain injury, spinal cord injury, AD, and PD." (PMID 33014276, 2020). "The role of Sirt-1 expression in regulating the activition of the NLRP3 inflammasome induced by cerebral ischemia remains to be established." (PMID 32419986, 2020). "Increasing evidence suggests that SIRT1 is a promising target for the treatment of cerebral ischemia injury." (PMID 33014276, 2020). "The antioxidant effect of alpha-lipoic acid through the up-regulation of SIRT1-dependent PGC1-α expression has also been reported in a rat cerebral ischemia model." (PMID 30983970, 2019). "Previous studies have reported SIRT1 to be abnormally expressed in the ischemic penumbra of cerebral ischemia/reperfusion (I/R) injury rat model." (PMID 31920915, 2019). "The activation of SIRT1, cerebral-protection of melatonin against oxidative stress and apoptosis, relieves cerebral ischemia reperfusion injury, which was reversed by EX527." (PMID 31450679, 2019). "In the central nervous system diseases including cerebral ischemia, traumatic brain injury, Alzheimer's disease and Parkinson's disease, SIRT1 has shown protective effects due to its functions in metabolism, stress resistance, and genomic stability." (PMID 31920915, 2019). "The results from in vitro and in vivo studies demonstrate that increased autophagy through SIRT1-dependent TSC2-mTOR-S6K1 signaling is also involved in Nampt-induced neuroprotection in cerebral ischemia." (PMID 30416425, 2018).
Cerebral ischemia (continued). "In this review, we will focus on the roles of SIRT1 in the brain in metabolism, circadian rhythm, and SIRT1 function in the context of cerebral ischemia and neurodegenerative disorders." (PMID 30532738, 2018). "The purpose of present study is to investigate the effects of BHD on angiogenesis in rats after cerebral ischemia/reperfusion (I/R) injury targeting Silent information regulator 1 (SIRT1) / Vascular endothelial growth factor (VEGF) pathway." (PMID 30564092, 2018). "In recent years, Sirt1 has been found to be neuroprotective against cerebral ischemia/reperfusion (I/R) injury." (PMID 30519156, 2018). "Collectively, the evidence gathered here demonstrates the pivotal role SIRT1 plays against cerebral ischemia." (PMID 30532738, 2018). "Since the SIRT1 inhibitor sirtinol reversed the effect of resveratrol, SIRT1 activity seems to be required for resveratrol-mediated neuroprotective effects in cerebral ischemia." (PMID 30416425, 2018). "Overexpression of Nampt reduces ischemic infarct in experimental cerebral ischemia rats, and SIRT1 global knockout blocks this effect." (PMID 30416425, 2018). "In vivo, both SIRT1 expression and activity were reduced 6 hours following experimental cerebral ischemia and its expression was decreased 7 and 14 days after traumatic brain injury." (PMID 24586272, 2014). "The neuroprotective effect of SIRT1 was first reported in ischemic preconditioning and the SIRT1 activating compound resveratrol reduced neuronal injury of the hippocampus in global cerebral ischemia in rats." (PMID 23888142, 2013). "To determine if IPC alters mitochondrial levels of SIRT1, we exposed rats to 2 min of global cerebral ischemia with systemic hypotension to induce IPC." (PMID 24058702, 2013). "We have previously demonstrated that IPC activates nuclear SIRT1 deacetylase activity and SIRT1 mediated neuroprotection against cerebral ischemia." (PMID 24058702, 2013). "Current studies have shown that Momordica Charantia polysaccharides can promote β‐catenin deacetylation by upregulating Sirt1 after cerebral ischemia–reperfusion injury, thereby promoting the transformation of NSC differentiation potential from glial cell lines to neurons." (PMID 39915897, 2025). "In addition, studies have demonstrated that the deacetylation of FoxO1 by Sirt1 exhibits a neuroprotective impact on oxidative stress following cerebral ischemia-reperfusion." (PMID 40160465, 2025). "Once activated, SIRT1 exerts neuroprotective effects by deacetylating and downregulating NLRP3 inflammasome-associated molecules, thereby mitigating inflammation and alleviating cerebral ischemia-reperfusion injury." (PMID 40356977, 2025). "SIRT1 is downregulated after cerebral ischemia/reperfusion injury." (PMID 38767771, 2024). "Overexpression of SIRT1 in BMECs rescued claudin-5, occludin, ZO-1, and VE-cadherin expression, while stabilizing claudin-5/ZO-1 interactions to protect against senescence-induced brain endothelial barrier hyperpermeability, cerebral ischemia, and OGD/R." (PMID 39598406, 2024). "Additionally, in rat models of cerebral ischemia, miR-199a-5p inhibition has induced ischemic tolerance by upregulating Sirt1." (PMID 39596440, 2024). "Modulating the SIRT1/Mapt pathway could potentially have a significant impact on stroke recovery and cerebral ischemia/reperfusion function." (PMID 38745725, 2024). "The SIRT1 inhibitor sirtinol abolishes the neuroprotective effect of citicoline in rats with brain ischemia, suggesting that citicoline may exert its neuroprotective effects by enhancing SIRT1 expression." (PMID 39143698, 2024). "The increased expression of SIRT1 after cerebral ischemia may represent an endogenous defense mechanism as a stress response." (PMID 37627275, 2023). "Besides inhibiting neuronal apoptosis and necrosis, Nampt promotes neuronal survival through inducing autophagy via regulating TSC2-mTOR-S6K1 signaling pathway in a Sirt1-dependent manner during cerebral ischemia." (PMID 37622049, 2023).
Cerebral ischemia (continued). "Therefore, it is rational to conclude that magnoflorine relieved cerebral ischemia-induced neuronal damage by activating the SIRT1/AMPK pathway." (PMID 37627275, 2023). "Sirt1 can alleviate cerebral ischemia/reperfusion injury by regulating NF-κB pathway." (PMID 37622049, 2023). "Meanwhile, the neuroprotective roles of Sirt1, an NAD+-dependent protein deacetylase that has been traditionally linked with calorie restriction and aging, in the context of cerebral ischemia and neurodegenerative disorders, have attracted more and more attention." (PMID 37190639, 2023). "Their findings indicate that circHIPK3 may play a role in the pathogenesis of cerebral ischemia by modulating the miR-148b-3p/SIRT1 axis." (PMID 37627275, 2023). "In addition, a very recent study also determined that Tet attenuated cerebral ischemia/reperfusion injury by inhibiting NLRP3 via Sirt-1, which silenced many key genes involved in this NLRP3 pathway." (PMID 34417574, 2022). "Enhanced expression of SIRT1 could inhibit brain damage and prevent delayed cerebral ischemia in experimental SAH." (PMID 36439686, 2022). "An in vitro study demonstrated that nicotinamide (a SIRT1 inhibitor) protects neurons against excitotoxicity and prevents NAD+ depletion, whereas SIRT1 may impair energetically compromised neurons by consuming NAD+ in cerebral ischemia." (PMID 36507335, 2022). "Therefore, the clinical and experimental studies both suggest resveratrol as a possible treatment for cerebral ischemia that targets the SIRT1-mediated autophagic pathway." (PMID 36507335, 2022). "Moreover, quercetin mitigate cerebral ischemia reperfusion injury and reduce ROS generation in the mitochondria via SIRT1/Nrf2/HO-1 pathway." (PMID 35935939, 2022). "Besides SIRT1, modulation of the activity of other sirtuins can also influence the progress or outcome of cerebral ischemia." (PMID 34680562, 2021). "Importantly, accumulating evidences have shown that brain SIRT-1 plays neuroprotective roles in the context of neurodegenerative disorders and cerebral ischemia." (PMID 32831997, 2020). "Moreover, cerebral ischemia injury has been shown to be attenuated by short-term caloric restriction via upregulation of SIRT1 expression." (PMID 33510613, 2020). "Likewise, lncRNA SNHG12 was found to upregulate SIRT1 by targeting miR-199a, consequently restarting cerebral ischemia/reperfusion injury." (PMID 31889905, 2019). "The neuroprotection against cerebral ischemia by SIRT1 is achieved through multiple mechanisms." (PMID 30532738, 2018). "Thus, we aim to investigate the effects of BHD on angiogenesis in rats after cerebral ischemia/reperfusion (I/R) injury through SIRT1/VEGF pathway." (PMID 30564092, 2018).
Cerebral ischemia (continued). "The protective effect of NBP on cerebral ischemia/reperfusion may be achieved through SIRT1." (PMID 37056986, 2023). "HGWD may alleviate cerebral ischemia injury via Sirt1/NF-κB/NLRP3 inflammatory signaling pathway." (PMID 37650573, 2023). "The protection provided by NBP against cerebral ischemia/reperfusion may be achieved through SIRT1." (PMID 37056986, 2023). "Thus, the antioxidant property of SIRT1 might contribute to the neuroprotective effects of DSS against cerebral ischemia-reperfusion injury." (PMID 33935765, 2021). "Thus, SIRT1 signaling could be one of the therapeutic targets of DSS against cerebral ischemia-reperfusion injury." (PMID 33935765, 2021). "In the CNS, SIRT-1 plays an important role in promoting neurodevelopment, delaying brain senescence, maintaining homeostasis, and modulating circadian rhythm and has also been demonstrated as the neuroprotective roles under the condition of neurodegeneration and cerebral ischemia." (PMID 32831997, 2020). "Furthermore, several studies have suggested that activation of SIRT1 may rescue mitochondrial function and inhibit apoptosis in cerebral ischemia and neurodegenerative diseases." (PMID 28848394, 2017). "When cerebral ischemia/reperfusion injury (CIRI) occurs, downregulation of SIRT1 weakens its interaction with RIP1, facilitating necrosomes formation, and thus exacerbates necroptosis." (PMID 40008377, 2025). "Aging, cerebral ischemia, and OGD/R have been shown to reduce the expression of SIRT1, occludin, claudin-5, VE-cadherin, and ZO-1 in BMECs, leading to dysregulated BBB permeability." (PMID 39598406, 2024). "SIRT1 enhances the mitochondrial structure repair and functional recovery by activating SIRT3 after cerebral ischemia/reperfusion injury in rats, thereby promoting neurological function." (PMID 38767771, 2024). "Organic SIRT1 modulators also ameliorated brain injury in middle cerebral artery occlusion/reperfusion (MCAO/R) and OGD/R models of cerebral ischemia." (PMID 39598406, 2024). "SIRT1 can increase the deacetylation of SIRT3 and enhance the activity of SIRT3 after cerebral ischemia/reperfusion injury." (PMID 38767771, 2024). "The results showed that NAD+ and NBP had similar neuroprotective and antioxidant effects in cerebral ischemia, while NAD+ had better ability in restoring energy metabolism, possibly through upregulating the activity of SIRT1 and SIRT3." (PMID 37056986, 2023). "A recent study also showed that astragaloside IV exerted neuroprotective effects in rats with cerebral ischemia/reperfusion (CIR) injury, probably through the Sirt1/Mapt pathway." (PMID 35991562, 2022). "Sirt1, a member of the HDAC superfamily, plays an important role in neuroprotection and is related to anti-inflammatory effects in cerebral ischemia because its inhibition exacerbates ischemic injury accompanied by an increased acetylation of NF-κB." (PMID 36076942, 2022). "•The present study preliminarily showed that regulating SIRT1 can further affect MAPT protein, providing a new idea to the pathogenesis of cerebral ischemia." (PMID 33841157, 2021). "It was found that SIRT1 inhibited the activation of NLRP3 and the secretion of IL-1β in cerebral ischemia." (PMID 34039367, 2021). "SIRT1, SIRT2, and SIRT3 have the highest deacetylase activities and can exert great neuroprotective effects in cerebral ischemia." (PMID 33149812, 2020).
Cerebral ischemia (continued). "A previous study has highlighted the neuroprotective effect of TSG on cerebral ischemia, which was regulated by inhibiting iNOS, JNK, and NF-κB and activating SIRT1." (PMID 31379960, 2019). "Consistent with this, in a global cerebral ischemia model of bilateral common carotid artery occlusion (BCAO), SIRT1-Tg mice showed significantly preserved cerebral blood flow during BCAO, which was absent in their wild-type littermates." (PMID 30532738, 2018). "Previous research has shown that mice overexpressing SIRT1 in the brain experience diminished hippocampal damage induced by cerebral ischemia compared to mice lacking SIRT1 expression." (PMID 39273230, 2024). "Likewise, we found that SIRT1 overexpression downregulated the levels of MDA and ROS, enhanced the activities of GSH-Px and SOD in cerebral ischemia, which were respectively reversed by SIRT1 interference." (PMID 38767771, 2024). "Interestingly, by activating SIRT1, MAR1 treatment exerted a neuroprotective effect in mice and thus had a therapeutic effect on cerebral ischemia-reperfusion injury." (PMID 33557833, 2021). "Given the diverse role of both SIRT1 and PGC-1α in regulating cellular metabolism and homeostasis, this is known to exert protective effects in various acute and chronic neurological diseases, such as cerebral ischemia and neurodegenerative diseases." (PMID 31340436, 2019). "Interestingly, PARP1 activation is known to dysregulate SIRT1 activity via NAD+ depletion during skeletal muscle fatigue, aging, and cerebral ischemia, and deletion of PARP1 results in increased SIRT1 activity, higher mitochondrial content, and increased energy expenditure." (PMID 37744380, 2023). "This study showed that the expression of SIRT1 in the MCAO group decreased, while 14, 15‐EET treatment promoted the phosphorylation of AMPK and then upregulated the expression of SIRT1, thereby regulating mitochondrial dynamics and reducing neuronal injury induced by cerebral ischemia–reperfusion." (PMID 37017405, 2023). "Researchers have proven that the activation of AMPK/Sirt-1/PGC-1α helps to promote the biogenesis of mitochondria in adipocytes, maintain mitochondrial function, and inhibit oxidative stress, apoptosis, and mitochondrial damage during cerebral ischemia and myocardial ischemia." (PMID 35889753, 2022). "Upstream regulators of mitochondrial biogenesis, e.g., transcription factors such as SIRT1 (silent mating-type information regulation 2 homolog 1) and PGC1-α (peroxisome proliferator-activated receptor gamma coactivator-1 alpha) play key roles in the pathophysiology of brain ischemia." (PMID 30983970, 2019).